ENSG00000204003 (novel protein)
Gene: Protein-coding gene on chromosome 9 (136,738,167 to 136,748,453, reverse strand). Ensembl gene ENSG00000204003.
Genetic constraint (gnomAD): Missense variants: 205 observed, 203.33 expected, observed/expected ratio (o/e) 1.01, 90% interval 0.9 to 1.13. Synonymous variants: 90 observed, 85.07 expected, observed/expected ratio (o/e) 1.06, 90% interval 0.89 to 1.26.